IL6 (interleukin 6)
Diseases named in the same sentence as IL6 in open-access papers (continued):
Sharing a sentence is not in itself a finding about the gene and the disease.
tumor (continued). "IL1β and other pro-inflammatory cytokines, such as IL-6 and IL-8, which are known to promote inflammatory signaling, tumor growth, and metastasis, are also produced by cancer-associated fibroblasts (CAFs)." (PMID 34901003, 2021). "IL-6 pathway is abnormally hyperactivated in several cancers triggering tumor cell growth and immune system inhibition." (PMID 34576335, 2021). "The secretion of IL1A and IL6 in the serum of patients with higher HIF1α mRNA expression was significantly higher than the patients with lower HIF1α mRNA levels in tumor samples." (PMID 34362882, 2021). "IL-6 is a soluble glycosylated polypeptide chain and one of the major components of the tumour microenvironment that can be secreted by different neoplastic cells and stromal cells." (PMID 34256854, 2021). "Considering APA and tumor microenvironment are tightly closed with tumor, we preliminary explored its relation with the IL6-JAK-STAT3 pathway." (PMID 34660570, 2021). "Proinflammatory cytokines, particularly IL-6, secreted by both cancer cells and CAFs determine a malignancy-driven tumor microenvironment that promotes CCA progression." (PMID 33925189, 2021). "Lastly, we think that it exist the crosstalk between cancer cells and macrophages in muscle tissues, it is that tumor cells secrete IL-6 inducing macrophages to up-regulate MMP12 which degrade insulin and IGF-1 in muscle tissue." (PMID 34863141, 2021). "Interleukin 6 (IL-6) is one of the many cytokines used by tumor cells to facilitate invasion and metastasis." (PMID 33467681, 2021). "It was already well known that IL-6 regulates immune and inflammatory responses and is involved in tumor progression." (PMID 34393797, 2021). "Of course, further studies, especially with the targeted inhibition of EMT and IL-6, will be necessary in the future to better understand the mechanisms of WF and tumor cell interaction." (PMID 33922946, 2021). "On one hand, IL-6 induced PD-L1 expression on colorectal cancer cells thereby blunting anti-tumour effector function of CD8+ T cells." (PMID 34047814, 2021). "It is thus likely that SHH induced by KLF5KQ in tumor cells contributes to osteoclast differentiation by acting on osteoblasts to increase their release of IL-6." (PMID 33731701, 2021). "In the tumor microenvironment, IL-6/JAK/STAT3 signaling induced the expression of factors that promotes angiogenesis such as VEGF and invasiveness such as matrix metalloproteinases, while strongly suppressing the antitumor immune response." (PMID 33917399, 2021). "In the majority of clinical studies on patients with different types of cancer, the IL-6 serum levels increase, possibly reflecting a tumor-type-independent systemic phenomenon." (PMID 33461943, 2021). "PGCCs can use IL-6 protein as a paracrine mechanism to facilitate the transformation of fibroblast to more tumor promoting CAFs for chemoresistance, supporting the established role that the TME plays a critical role in tumor development and chemoresistance." (PMID 34588424, 2021). "Pro-inflammatory cytokines IL-1β, IL-6 and IL-8 are expressed in the tumor microenvironment and promote tumor growth." (PMID 33235296, 2020). "CRS refers to an elevated state of circulating level of cytokines, chemokines and other signaling proteins including interleukin 6 (IL-6) and interferon γ as a result of tumor lysis." (PMID 33042104, 2020). "RANKL and other osteoclast stimulating factors, including Interleukin-6 (IL-6) and Interleukin-11 (IL-11), are also secreted by tumour cells in bone metastases and OS, leading to an increase in bone resorption." (PMID 32752092, 2020). "Due to IL-6, this cell population showed a 2.5-fold increase in the EpCam+CD44hiCD24–/low and 2-fold decrease in the EpCam+CD44lowCD24– subpopulations of tumor stem cells; the formation of mammospheres was also observed." (PMID 32523653, 2020).
tumor (continued). "Therefore, researchers detected the expression of STAT3 phosphorylation and Snail in tumor cells interacted with TAMs and tumor-associated endothelial cells expressing or overexpressing B-cell lymphoma-2 (Bcl-2), which could promote the secretion of IL-6." (PMID 32161718, 2020). "Plasma interleukin-6, thrombopoietin, and serum chromogranin A and -B were measured; furthermore, tumor tissue was immunohistochemically stained for CgA+." (PMID 33383764, 2020). "To study if this overcoming of immune evasion by inhibition of IL6 signaling is due to decreased lactate efflux by tumor cells, we inhibited lactate efflux by inhibiting CA9." (PMID 33177492, 2020). "These cytokines are believed to promote tumor growth by supporting angiogenesis, although the pro-tumorigenic role of IL-6 is still inconclusive." (PMID 32331230, 2020). "Special attention should be paid to IL-6 due to its tumor promoting role observed in mice under particular PDT regimens." (PMID 31991650, 2020). "Using a bone metastatic mouse model, the suppression of IL-6 expression in human PC-3MM2 cells, along with clodronate liposome treatment resulted in decreased tumor size, osteoclast formation, and lowered lymph node metastasis when compared to control animals." (PMID 32585812, 2020). "Tumor-produced IL-6 and PGE2 led to increased levels of activated Signal Transducer and Activator of Transcription 3 (STAT3) and decreased levels of activated STAT1 and STAT6, respectively." (PMID 32656079, 2020). "We also noted that the tumor-infiltrating CD11b+CCR8+ cell subset responsible for the production of the greatest levels of the pro-inflammatory (IL-6, CCL3, CCL4) and pro-angiogenic (VEGF) factors among intra-tumoral myeloid cells." (PMID 31811337, 2020). "For instance, tumor hypoxia is known to upregulate genes such as IL-6 in macrophages, which, as we have seen, regulates BCSCs." (PMID 33371274, 2020). "As a proinflammatory mediator, IL-6 binds to gp130 in the tumor microenvironment, resulting in the phosphorylation of STAT3 after JAK activation." (PMID 33082817, 2020). "This represents a mode of recurrence in which some signal—perhaps a secreted paracrine-acting factor such as IL-6—can induce the reactivation of residual tumor cells en masse." (PMID 33024122, 2020). "IL-6 is a pro-inflammatory cytokine produced in tumor cells and activates the STAT3 pathway through binding to the IL-6 receptor." (PMID 32150979, 2020). "Here, chemerin lowered the release of IL-6 from tumor-adjacent endothelial cells and granulocyte-macrophage colony-stimulating factor from tumor cells." (PMID 33066326, 2020). "In several reports, IL-6 has been shown to play a key role for promoting the cancer cell malignancy in the tumor microenvironment." (PMID 33346211, 2020). "Concentrations of tumor-promoting cytokines, including IL-6, VEGF, TGF-β, and TNF-α were determined in the serum of NSCLC patients and controls using ELISA." (PMID 33125430, 2020). "The systematically positive effect of IL-6 on tumor survival must be accounted for: IL-6 binds to soluble IL-6R (sIL-6R), which interacts with gp130 on tumor cells." (PMID 32867390, 2020). "In murine PDAC, tumor cell-derived G-CSF impaired differentiation of type 1 conventional dendritic cells in the bone marrow and blood, and elevated serum levels of the cytokine IL-6 in tumor-bearing mice induced apoptosis of conventional dendritic cells." (PMID 33597954, 2020). "We previously demonstrated that AN-exposed gingival fibroblasts secrete various tumor promoting cytokines, including Gro-α, IL-6 and IL-8." (PMID 32856877, 2020). "Pro-inflammatory cytokines, including TNF-α, IL-1α, IL-1β, and IL-6, in the tumor microenvironment have been reported to promote tumor progression, metastasis, and invasion." (PMID 33348858, 2020). "Tumor-associated angiogenesis is driven by various cytokines including vascular endothelial growth factor (VEGF), CXCL8, IL-6, and TGFβ." (PMID 32585812, 2020).
tumor (continued). "It has also been reported that IL-6 can stimulate tumor infiltration by macrophages, and this phenomenon is associated with worse prognosis of OC patients." (PMID 33062717, 2020). "The expression analysis indicated a significantly higher transcriptional level of HIP-55 in tumor tissues compared with normal tissues (P < 0.01), and IL-6 was lower expression in tumor tissue compared to normal tissue." (PMID 32134471, 2020). "An inverse correlation was found between the amount of muscle IL-6, the amount of circulating adiponectin and the amount of tumour MMP3." (PMID 32472095, 2020). "Collectively, results suggest that M2 macrophages are activated in grade I tumour tissue although, due to the variability in the expression levels for IL-6, TGF-beta and TNF-alpha in individual samples, these results were not significant." (PMID 32070062, 2020). "Exosomes isolated from B16 melanoma tumors in mice were shown to stimulate MDSCs to produce TNFα, MCP1, and IL6 in a MyD88-dependent manner, which promotes immunosuppression, tumor growth, and metastasis." (PMID 32547552, 2020). "In conclusion, secretion of the cytokine IL-6 is one important mechanism by which CAFs can enhance chemoresistance of tumor cells." (PMID 32528731, 2020). "Activated macrophages and CD4+ effector T-cells release tumor-promoting cytokines interleukin 6 (IL-6)." (PMID 33291412, 2020). "Inhibiting the IL-6/STAT3 signaling pathway correspondingly shifts macrophages to the M1 polarization phenotype, and blocking the IL-6/STAT3 signaling pathway can dramatically reduce tumor formation." (PMID 32904108, 2020). "Currently, accumulating studies have demonstrated that chronic inflammation related to cellular senescence plays a key role in tumor immunosuppression and major proinflammatory factors, including IL-1α, IL-1β, IL-6 and IL-8." (PMID 33232279, 2020). "We tested the effect of inflammatory cytokines commonly found in tumor microenvironment including IL-1β, IL-6, IL-10, TNF-α, and IFN-γ on TDO2 expression on MUM cells." (PMID 32050636, 2020). "In preclinical study, tumor cells use PI3K-hypoxia-inducible factor 1α axis to polarize macrophages into tumor-associated macrophages (TAMs), which produce IL-6 after engulfing particles released by tumor cells." (PMID 33537237, 2020). "We focus on the killing effect and mechanisms of macrophages on tumors, while tumor promoting factors such as IL-6, IL-8, IL-10, TLR4 are briefly introduced as well." (PMID 32161718, 2020). "Interleukin 8 (IL-8) similarly to IL-6 is involved in the progression of tumor growth and promotes angiogenesis, proliferation, and migration of cancer cells." (PMID 32963755, 2020). "MM cells can induce OCs differentiation and osteolytic activity, by modulating release from OBs of the proinflammatory cytokine IL-6 inside the tumor microenvironment; in turn, IL-6 inhibits OBs activity and induces the production of RANKL." (PMID 32916806, 2020). "IL-6+/-/Pax5+/- tumor DNA was derived from whole leukemic BM or lymph nodes, while tail DNA of the respective mouse was used as reference germline material." (PMID 33154497, 2020). "Tumor-associated Macrophages (TAMs) secrete immunosuppressive cytokines TGF-B, IL-6, IL-10 that result in downregulation of costimulatory molecules and MHC expression lead to reduced phagocytic activity and reduced anti-tumor immunity." (PMID 33281826, 2020). "Stat3/NF-κB pathways in tumor and stromal cells are activated by inflammatory cytokines such as IL-1β, IL-6, and IL-8 to further secrete cytokines in a positive feedback loop that elicits angiogenesis, CSC self-renewal, and metastasis." (PMID 32211043, 2020). "Studies demonstrated IL-6 role in tumor angiogenesis, which is an essential potential in IL-6 targeted therapy." (PMID 32399323, 2020). "However, the activity of IL‐6 and its receptor signals being completely inhibited may lead to a weakened immune system, bone marrow suppression and an increased risk of infection and tumours." (PMID 32530555, 2020).
tumor (continued). "Serum levels of IL-6 are elevated in patients with metastatic and CRPC and, IL-6 significantly correlated with tumor stage, and it is inversely correlated with tumor survival and therapeutic response." (PMID 33076397, 2020). "When treated with mAb targeting IL-6, these mice harbored fewer and smaller lung lesions, less evident lung surface neoplasms, a prominent 46% reduction in the proliferation of tumor cells, and a downregulation of Stat3 activation." (PMID 32117295, 2020). "CXCL1, CXCL2, and CXCL5 have been shown to recruit MDSCs to the pre-metastatic niche through the interaction with CXCR2; once in the pre-metastatic site, MDSCs favor tumor cell recruitment and seeding by secreting TNFα, TGFβ, IL-6, CCL2 and CXCL2." (PMID 32823961, 2020). "The secretion of IL‐6 from the cancer cells was determined in both culture and tumour‐bearing mice by a species‐specific ELISA." (PMID 31436048, 2020). "All together, these results firstly suggested that GCAFs promote VM formation and tumor growth in GBC via upregulating NOX4 expression through paracrine IL-6 mediating IL-6/JAK/STAT3 signaling pathway." (PMID 33153467, 2020). "It has been shown that high levels of IL6 secretion can lead to increased tumor invasion, proliferation and resistance to chemotherapy." (PMID 32560387, 2020). "Several studies demonstrated the role of IL6-mediated pro-proliferative, anti-apoptotic, angiogenic, metastatic, and immunosuppressive responses in tumor development and progression." (PMID 32219066, 2020). "When BC cell lines cocultured with mature adipocytes, adipocyte-derived leptin and IL-6 promoted local invasion and eventually metastasis of tumor cells via activation of lysyl hydroxylase 2 (PLOD2)." (PMID 32787888, 2020). "Neutralization of macrophage-derived IL-6 or inhibition of PGK1 T243 phosphorylation or PDPK1 in tumor cells markedly abrogates macrophage-promoted glycolysis, proliferation, and tumorigenesis." (PMID 33505964, 2020). "In contrast, given the pro-tumorigenic role for IL-6 in vivo and decades of work establishing its ability to promote tumor cell survival, invasion, and metastasis, there has been great interest in the therapeutic targeting of IL-6/JAK/STAT signaling." (PMID 32023849, 2020). "In patients with several types of cancer, including NSCLC, high serum IL-6 levels are related to tumor stage, size, metastasis, and survival." (PMID 33167343, 2020). "CRP levels are well known to correlate with IL-6, a pro-cachectic pro-inflammatory cytokine known to be elaborated by some tumor cells." (PMID 33291708, 2020). "In the TME, tumour-derived TGF-β inhibits IFN-α, TNF-α, and IL-6 production in tumour-associated plasmacytoid dendritic cells (pDCs) to foster their immune tolerance functions." (PMID 33114183, 2020). "This is accompanied by a reduction of recruited inflammatory cells into the TME and expression of tumour-promoting cytokines such as IL-6 and an improved response to anti-programmed death receptor-1 (PD-1) treatment." (PMID 33116132, 2020). "The production of pro-inflammatory IL-6 and IL-1β can also drive this inflammation in the tumor microenvironment (TME)." (PMID 32098318, 2020). "IHC analysis demonstrated that the immunostaining of IL-6 was detected predominantly in the cytoplasm of tumor as well as stromal cells while the staining of integrin β6 in the cytoplasm and membrane of tumor cells." (PMID 32855767, 2020). "Its expression is enhanced in astrocytes by the upregulation of IL-6 and IL-8 expression in tumor cells." (PMID 33262947, 2020). "Although miR‐223 enhanced IL‐6 expression in CSCC cells to some extent, the difference in the IL‐6 levels exhibited in the tumor tissues (TCGA cohort) was considered to be contributed by other cells." (PMID 32491253, 2020). "IL‐6 is secreted by certain cells, including t lymphocytes, tumor cells, and peripheral blood mononuclear and normal cells." (PMID 33201589, 2020).
tumor (continued). "In other words, IL-6 secretion after exercise training can have beneficial effects, including blood sugar regulation, lipolysis, inhibition of tumor growth, and maintenance of muscle mass." (PMID 32295130, 2020). "PTHrP can also directly induce OC differentiation and maturation by promoting secretion of IL-8, IL-6, IL-11, and other OC differentiation factors in tumor cells." (PMID 32269963, 2020). "Among women with metastatic breast cancer, circulating tumor cells have been found to be associated with circulating C-reactive protein (CRP) and circulating interleukin-6 (IL-6), among other inflammatory markers." (PMID 33302472, 2020). "aPSCs exert their tumor-promoting effect by recruiting suppressive subtypes of immune cells in the stroma by secreting IL-6 M-CSF." (PMID 32823814, 2020). "The so-called tumor microenvironment comprises numerous cell types of the inflammatory system that are able to produce specific cytokines (i.e., interleukin-6) in the presence of cancer cells and tumor-related necrosis." (PMID 31936329, 2020). "This study detected decreased IL-6 levels in tumor-bearing mice that were injected with anti-RCC2 siRNA-transfected MCF-7 cells." (PMID 32565805, 2020). "CCR6 signaling also promotes murine transplantable colon cancer by recruiting macrophages to the TME through a CCL2-CCR6 axis, which results in the release of IL-1β, IL-6, and TNFα, further enhancing tumor progression." (PMID 32733461, 2020). "A previous study showed that production of IL-6 was increased in tumor tissue and serum of patients with CRC." (PMID 32317968, 2020). "IL-6 is not only related to advanced tumor stages and poor survival of CRC patients but also promotes the motility of CRC cells." (PMID 32855767, 2020). "Our results showed that treatment with stromal IL6 increased genes involved in glucose metabolism, specifically glycolysis, that decreased when IL6 receptor on tumor cells was silenced by siRNA for IL6R in SU86.86." (PMID 33177492, 2020). "Upregulation of S1PR1 triggers the stimulation of tumor-infiltrating macrophages and dendritic cells and increases IL-6 concentrations in CAC." (PMID 32357539, 2020). "Based on the LTB chip, we successfully confirmed the inflammatory cytokine, interleukin 6 (IL-6), -mediated intercellular communication in the tumor microenvironment during lymphatic metastasis." (PMID 33659239, 2020). "Previous studies have indicated that a high level of IL-6 is associated with HCC and plays an important role during HCC tumor initiation, progression, and recurrence." (PMID 32257389, 2020). "In our experiments, IL-6 was increased in the tumor group and showed a decreased fat amount, compared to healthy mice." (PMID 33086629, 2020). "Increased IL-6 levels have been observed in the serum and tumor microenvironment, and all immune cells (such as NK cells, effector T cells, and DCs) in the tumor microenvironment express IL-6R." (PMID 33363013, 2020). "For example, does poly(I:C) affect the anti‐tumour activity of local‐infiltrated macrophages by IL‐6?" (PMID 31943744, 2020). "IL-6/STAT3 signaling in tumor-containing lung tissue is activated via reciprocal interactions between metastatic tumor cells and stromal cells." (PMID 33322216, 2020). "Intriguingly, and in contrast to our observations, several recent studies have shown that combined blockade of IL-6 and PD-1/PD-L1 checkpoint molecules promotes tumor infiltration of IFN-γ-producing CD4+ T cells and exerts synergistic antitumor effects." (PMID 32107566, 2020). "We treated TC-1 tumor-bearing mice with neutralizing anti-G-CSF and/or anti-IL-6 and observed a significant decrease in tumor growth compared to the control group treated with irrelevant antibody." (PMID 33330068, 2020). "The M2d type is activated by IL-6 and enhances the induction and growth of tumor cell masses through angiogenesis." (PMID 32726950, 2020).